IL6 (interleukin 6)
Diseases named in the same sentence as IL6 in open-access papers (continued):
Sharing a sentence is not in itself a finding about the gene and the disease.
colitis (continued). "The levels of TNFα, IL-1β, and IL-6 in colon tissues of WT mice remained high at d 6 post DSS challenge, correlated with severe tissue damage and worse colitis outcome as observed above." (PMID 31555304, 2019). "The sedentary mice fed HFD with experimental colitis presented significantly higher colonic tissue content of TNF-α, IL 1β, IL-6, IL-17, INFγ, and IL-10 as compared with the respective values of these cytokines recorded in sedentary mice fed SD (p < 0.05)." (PMID 31117199, 2019). "As a mediator of IL-6-induced STAT3 activation, TRIM27 plays important roles in DSS-induced colitis and AOM/DSS-induced CAC development." (PMID 30143645, 2018). "Levels of proinflammatory cytokines, such as TNF, IFN-γ, IL-6, IL-12, IL-17A, and IL-23 were elevated in the serum of DSS-induced colitis mice." (PMID 29892282, 2018). "Genetic studies have shown that inflammatory cytokines, such as TNFα, IL-1β, IL-6, and IFN-γ, are elevated in colitis, and are important in the development of mucosal inflammation." (PMID 29467753, 2018). "The protein levels of two inflammatory mediators IL-6 and TNF-α were found to have changed in the group with TRYP treatment compared with the untreated colitis group." (PMID 29724065, 2018). "Our present study showed that the induction of colitis by DSS led to damage and inflammatory infiltration of the colonic mucosa and increased the mucosal concentration of TNF-α, IL-1β and IL-6." (PMID 29495327, 2018). "Increases in the level of TNF-α, IL-6 and IL-1β during IBD and experimental colitis have been well documented." (PMID 30024891, 2018). "The pro‐inflammatory cytokines IL1A, IL1B, IL6, and CSF3 and chemokines CXCL1 and CXCL2 were significantly increased, and the frequency of CD11b+Ly6G+ neutrophils was higher in CD11c‐Cre+Rab32f/f colitis mice." (PMID 30338217, 2018). "In this study, we found that supplemented with Farrerol significantly suppressed the production of pro-inflammatory cytokines TNF-α, IL-6 and IL-1β in TNBS-induced colitis mice." (PMID 30011811, 2018). "We also noted that colonic levels of pro-inflammatory cytokines, such as INF-γ, IL6, IL1-β, TNF-α, and IL10, were significantly (P < 0.001) increased in mice with DSS-induced colitis, as compared to healthy mice." (PMID 28528363, 2018). "In the DSS-induced colitis mouse model, B. fragilis inhibits the expression of proinflammatory cytokines IL-6 and TNF-α and enhances the anti-inflammatory IL-10 expression, and thereby ameliorates colitis symptoms." (PMID 30060606, 2018). "The two strains with pathobiont characteristics appear to drive inflammation largely through GM-CSF, IL-6, and IFN-γ production—a cytokine signature known to actively contribute to colitis progression." (PMID 30356663, 2018). "Together, these data support the idea that VNS attenuates HMGB1 levels and affects the colonic immune response, mainly reducing IL-6 and CXCL1 production in oxazolone-induced colitis eventually leading to an improved survival." (PMID 29791477, 2018). "Compared with the normal group, mRNA levels of TLR4, NF-κB, IL-6, STAT3, and JAK2 in colitis rats remarkably increased (P < 0.001, P < 0.01)." (PMID 30042683, 2018). "The combination drug modulated the production of both proinflammatory cytokines (IL-6, IL-1β, and IL-17) and an anti-inflammatory cytokine (IL-10) in mice with DSS-induced colitis." (PMID 29466999, 2018). "In the colitis phase of CAC, IL-6-polarised M2-like macrophages express the chemokine CCL-20 that recruits CCR-6-expressing lymphocytes, further promoting CAC progression." (PMID 29695802, 2018). "We conclude that TRYP improves the health condition of mice with DSS induced colitis by regulating the TNF-α/NF-κBp65 and IL-6/STAT3 signaling pathways via inhibiting the degradation of IκBα and the phosphorylation of STAT3." (PMID 29724065, 2018). "Increased IL-6 production by the lamina propria and CD4+ T cells has been reported in experimental colitis models." (PMID 30289911, 2018).
colitis (continued). "In fact, as in TNBS-induced colitis, VNS reduced the serum levels of pro-inflammatory cytokines, i.e. IL-6, CXCL1, and TNFα, and dampened the colonic expression of IL-6 and CXCL1 in the oxazolone-induced colitis model." (PMID 29791477, 2018). "In colitic models, exogenous administration of IAP improved the macroscopically and microscopically finding of colonic inflammation through inhibition of LPS-induced production of TNF-α and IL-6 and TLR-4 dependent pathway." (PMID 30558547, 2018). "PSMP overexpression in the colon aggravated the DSS-induced colitis and the anti-PSMP neutralizing antibody mollified the colitis by reducing macrophage infiltration and inhibiting the expression of IL-6, TNF-α and CCL2." (PMID 28698550, 2017). "The expression of mRNA for TNF-α, IL-6 and MCP-1 was significantly decreased in the mesenteric white tissue of the mice with TNBS colitis subjected to voluntary exercise as compared to the group maintained without voluntary exercise (p < 0.05)." (PMID 28425943, 2017). "To analyze if the helminth mediated increase in IL-6 and CXCL1 promoted the increased disease severity of DSS-induced colitis, we infected BALB/c mice with 200 third-stage larvae of H. polygyrus 6 days before DSS administration." (PMID 28938014, 2017). "Increased serum and tissue levels of pro-inflammatory cytokines such as IL-6, IL-1β and TNF-α are characteristic features of colitis and many other chronic inflammatory diseases." (PMID 28634361, 2017). "Tumour necrosis factor alpha (TNF-α), Interleukin 6 (IL-6), Interleukin 1 beta (IL-1β), and cyclooxygenase-2 (COX-2) play a pivotal role in the onset of colitis." (PMID 28415628, 2017). "The expression of mRNA for TNF-α, IL-6 and MCP-1 was significantly increased in the sedentary mice fed a HFD as compared to the sedentary mice with colitis fed a SD." (PMID 28425943, 2017). "Nuclear factor-kB participates in controlling the activation of various pro-inflammatory cytokine genes such as IL6, IFNγ or IL17 suggesting that NF-κB pathway is also turned off in MAM treated mice in DSS colitis model." (PMID 28203226, 2017). "Simultaneously, cytokines, including PSMP, IL-6, CCL2, TNF-α, IFN-γ and IL-10 in the colon homogenates were measured with CBA in the time-course study of colitis." (PMID 28698550, 2017). "The administration of monoclonal antibodies against IL-6 and TNF-α was able to reduce disease severity and attenuate intestinal inflammation in DSS-induced colitis." (PMID 28194046, 2017). "In IBD, several inflammatory cytokines, such as interleukin-1β (IL-1β), interleukin 6 (IL-6) and TNF-α, mediate the progression of colitis and CAC18–20." (PMID 28701727, 2017). "The intestinal macrophages of WT colitis mice expressed high levels of TNF-α, IL-1β, IL-6 and iNOS mRNA compared with the intestinal macrophages of WT normal mice." (PMID 28733636, 2017). "Compared with normal rats, the levels of many cytokines including IL-6, TNF-α, IL-17, IL-23, IL-1βand IFN-γ were increased, while IL-13, IL-10 and IL-4 were decreased in TNBS-induced colitis rats." (PMID 29113344, 2017). "In line with the results obtained in patients with CD, prolonged hypoxia downregulated NF-κB signaling and the expression of Tnfα, Il-6, and Il-1β in the DSS and Il-10−/−mouse models of colitis." (PMID 28740109, 2017). "IL-6, CCL2, TNF-α, and IFN-γ in the mIgG-treated colitis group were extremely elevated and significantly decreased in the 3D5-treated colitis group." (PMID 28698550, 2017). "Infiltrated neutrophils produce proinflammatory cytokines including IL-6, IL-17, and IFN-γ, and enhance the expression of oxidative stress enzyme, iNOS, further aggravating colitis." (PMID 28524086, 2017). "Here, we demonstrated that PSMP was expressed in the colonic mucosa of patients with colitis and significantly up-regulated in the initial stage prior to the expression of IL-6, TNF-α and CCL2 in a DSS-induced colitis in mice." (PMID 28698550, 2017).
colitis (continued). "The data in this paper revealed that the expression levels of IL-17, IL-21, IL-23, IL-6, IL-1β, TNFα, and IL-12 in mLN tissues significantly decreased in CD169-DTR colitis mice compared to those in WT colitis mice." (PMID 28694804, 2017). "The mRNA expressions of IL-1β, IL-6 and TNF-α in the colons of colitis mice significantly increased, and bergenin (20, 50 mg/kg) and 5-ASA (100 mg/kg) showed obvious inhibition." (PMID 29375382, 2017). "PSMP was up-regulated in the initial stage prior to IL-6, TNF-α and CCL2 up-regulated expression in DSS colitis and promoted the M1 macrophages to produce CCL2." (PMID 28698550, 2017). "IL-1β and IL-6 are crucial in IBD and arrest DSS-induced colitis by inhibiting the pro-inflammatory activity and possible downstream proangiogenic activity." (PMID 28556814, 2017). "Results are consistent with recent studies showing that SphK inhibitors significantly abrogate colitic damage and reduce the expression of IL-6 and COX-2, and with the enhancement of colitis severity and inflammation by deletion of S1PL in DSS mouse models." (PMID 28300788, 2017). "In a mouse model of DSS-induced colitis, intraperitoneal administration of ADM was shown to inhibit colon inflammation, and research has shown that administration of ADM reduces the levels of cytokines such as TNF-α, IL-1β, and IL-6." (PMID 28210268, 2017). "PSMP is up-regulated in the initial stage prior to IL-6, TNF-α and CCL2 up-regulated expression in DSS colitis and promote the M1 macrophages to produce CCL2." (PMID 28698550, 2017). "Defect in p47phox protein expression results in increased IL-6 and IL-17 expression in the chronic DSS colitis model." (PMID 28191009, 2017). "In this study, PSMP increases were observed in the initial stage in the DSS-induced colitis model; at this time, CCL2, IL-6 and TNF-α were still expressed at low level." (PMID 28698550, 2017). "Data from animal models indicate that OLE attenuates the inflammatory process in DSS-induced colitis by downregulating the expression of COX-2 and pro-inflammatory cytokines, such as TNF-alpha, IL-1β, IL-6 and IL-17." (PMID 28420140, 2017). "In contrast, the intestinal macrophages of p85α+/− colitis mice expressed similar levels of TNF-α, IL-1β, IL-6 and iNOS mRNA compared with intestinal macrophages of p85α+/− normal mice." (PMID 28733636, 2017). "Consistently, dietary white and dark kidney beans reduced the mRNA expression of IL-6, and cranberry bean supplementation reduced the IL-6 protein in the colon along with reduced serum IL-6, IL-17, and IFN-γ in DSS-induced colitis." (PMID 28524086, 2017). "We found an elevated protein expression of inflammatory cytokines including IL-6, IL-23, IL-1β, and TNF-α in the mucosa of colitis mice compared to the control group." (PMID 29375374, 2017). "Higher serum levels of IL-6 have been reported in colitis patients and DSS-induced experimental colitis, and it positively correlated with disease severity in colitis." (PMID 28584524, 2017). "Reduces inflammation in a mouse model of DSS-induced colitis, probably by increasing the expression of anti-inflammatory cytokines (IL-10 and TGF-β) and reducing pro-inflammatory ones (IL-6 and TNF-α)." (PMID 29163443, 2017). "Bergenin (50 mg/kg), 5-ASA (100 mg/kg) and rosiglitazone (20 mg/kg) significantly down-regulated the mRNA and protein expressions of IL-6 and TNF-α in colons of mice with DSS-induced colitis." (PMID 29375382, 2017). "Significantly higher levels of mRNAs of pro-inflammatory cytokines, IL-1β, IL-6, IL-17 and TNF-α, were found as early as day 6 in our colitis model than control group, showing ~5.7, ~6.7, ~12.0 and ~3.2 fold increase, respectively." (PMID 28854223, 2017). "The administration of HQD, however, significantly suppressed the accumulation of TNF-α, IL-6, IL-1β, and COX-2 in the colon tissues of mice with DSS-induced colitis." (PMID 28415628, 2017).
colitis (continued). "In contrast, such an elevation in the plasma levels of TNF-α, MCP-1, IL-6 and IL-13 was significantly attenuated in the HFD mice subjected to voluntary exercise prior to the induction of colitis (p < 0.05)." (PMID 28425943, 2017). "Butyrate treatment, however, resulted in significantly lower plasma levels of IL-6 and significantly higher levels of TGF-β when compared to the colitis group." (PMID 27473867, 2016). "The present study in vivo found that sodium propionate inhibited the up-regulation of proinflammatory factors IL-6, IL-1β, and TNF-α mRNA level in the colon of colitis mice." (PMID 27574508, 2016). "Compared with the control, the serum levels of IL-1β, IL-6, IL-10, IFNγ, and TNFα were increased in DSS colitis mice." (PMID 27177331, 2016). "Real time RT-PCR quantitation confirmed that pro-inflammatory cytokines and chemokines (CCL2, IL-1β, IL-6, IL-23, TNF-α, IL-17A and IL-17F) were elevated in quiescent and active colitis biopsies." (PMID 27271344, 2016). "In experimental colitis, macrophages and CD4+ T cells of the lamina propria produce an increased amount of IL-6." (PMID 27293323, 2016). "LL202 inhibited the high-production of IL-1β, IL-6 and TNF-α dramatically both in the colon and serum of DSS-induced colitis mice." (PMID 27590510, 2016). "Naringenin abrogated experimental colitis by downregulating proinflammatory mediators like iNOS, ICAM-1, monocyte chemoattractant protein-1, COX-2, TNF-α, and IL-6." (PMID 27635116, 2016). "Pro-inflammatory cytokines (TNF-α, IL-1β, and IL-6) levels and MPO activity from colitis rat colon tissue were significantly increased compared to those in sham group." (PMID 27303297, 2016). "GA regulates the levels of inflammatory mediators such as IL-6, TNF-α, and IL-1β in DSS-induced colitis in mice." (PMID 27110761, 2016). "In the case of acute colitis induced by DSS, short-term psychological stress has been shown to increase expression of IFN-γ, IL-6, and TNF-α, resulting in exacerbated colitis." (PMID 27500935, 2016). "The murine DSS-induced colitis model exhibits a distinct cytokine profile with elevated levels of TNF-α, IFN-γ, IL-1β, IL-6, and IL-12." (PMID 27293323, 2016). "Previous studies have described that the DSS-induced colitis model induced high amounts of Th1 cytokines (TNF-α, IL-1β, IL-6)." (PMID 27965594, 2016). "As analyzed by t-tests, circulating levels of KC (p = 0.0035, t = 3.377 df = 10), G-CSF (p = 0.039, t = 1.961 df = 10) and IL-6 (p = 0.0002, t = 5.211 df = 10) were significantly elevated in mice with DSS-colitis." (PMID 27658624, 2016). "IL6 neutralization significantly attenuated TRUC disease, including reduced colitis scores and reduced splenomegaly." (PMID 25917784, 2015). "IL-1β, IL-6 and TGF-β, which had high levels in colitis, were significantly decreased in the MSC treated group." (PMID 25889203, 2015). "In patients with IBD, the production of the inflammatory cytokines TNF-α, IFN-γ, IL-6, IL-1β, IL-10 and IL-12 are in agreement with the results of the TNBS model of colitis." (PMID 26561804, 2015). "In contrast, DSS-induced colitis switches from Th1/Th17-mediated acute inflammation (increased TNF-alpha, IL6, IL-17, and KC) to a predominant Th2-mediated inflammatory response in the chronic state." (PMID 25756273, 2015). "In accordance with our data, it was earlier shown that the retinoic acid, which has an immunomodulatory effect, ameliorates the TBNS colitis via inhibition of TNF-α, IL-6, IL-1β secretion and MPO activity in mice." (PMID 25853847, 2015). "In dextran sodium sulphate (DSS) induced colitis in mice, Embelin reduced the mRNA expression of TNF-α, IL-1, IL-6, and colonic MPO." (PMID 26347311, 2015). "We found a significant increase in the levels of IL-1β, IL-6, IL-17, TNF-α and IFN-γ in the plasma of mice with colitis." (PMID 25625560, 2015). "After induction of colitis, ATB increased onset of clinical disease, histologic score, and colonic IL-6." (PMID 26605545, 2015).
colitis (continued). "Our data also showed high levels of IL-1β, IL-6 and TNF-α in homogenates of colonic segment from mice with TNBS-induced colitis." (PMID 25853847, 2015). "There was a significant increase in the levels of IL-1β, IL-6, IL-17, TNF-α and INF-γ in the plasma of the mice with colitis." (PMID 25625560, 2015). "Current regimens utilized to combat inflammation in colitis include anti-TNF and anti-IL-6 therapies." (PMID 26448758, 2015). "We demonstrate that RasGRP3 transgenic overexpression inhibits TLR agonists-induced IL-6 production, decreases the inflammation severity of DSS-induced colitis and relieves the clinical scores of CIA." (PMID 25118589, 2014). "Although IL-6 has positive effects on regeneration, its role in DSS-induced colitis was shown to be detrimental." (PMID 24993179, 2014). "We have investigated the production of cytokines including IFN-γ, IL-1β, IL-6, IL-10, IL-12 (P40), IL-12 (P70), IL-17, and TNF-α in colonic mucosa of mice with experimental colitis." (PMID 24948848, 2014). "Our current study showed that direct stimulation of a cell line of colonic epithelial cells with IL-25 increased expression of IL-6, TNFα, as well as IL-8 and CCL2, providing a potential mechanism by which IL-25 contributes to DSS-induced colitis." (PMID 25937893, 2014). "During colitis, Lb CNRZ327 modulated the production of TGF-β, IL-6, and IL-12 in colonic tissue and of TGF-β and IL-6 in the spleen, and caused an expansion of CD4+Foxp3+ regulatory T cells in the cecal lymph nodes." (PMID 24465791, 2014). "In the current work we assessed the severity of colitis via an increase in colonic MPO content, colon weight and circulating IL-6 and IL-18 levels as well as by a decrease in colon length and body weight." (PMID 25414650, 2014). "Actually, the amounts of IL-6 and IL-17A secreted from the GPx1−/− × Cat−/− splenocytes were much less than those from WT splenocytes in DSS-induced colitis." (PMID 24743300, 2014). "Recently we demonstrated that brain stimulation of the CAP alleviates the disease severity and suppresses colonic proinflammatory cytokine (IL-6, IL-1β and TNF-α) levels in experimental DSS-induced colitis." (PMID 25295619, 2014). "IL-6 and TNFα expression levels were increased in all treatment groups following DSS-induced colitis; however, the largest increases were observed in WTWTBM mice." (PMID 25460165, 2014). "Further studies are warranted to investigate the effect of XLS on these proinflammatory cytokines, such as IL-6, IL-17, and TNF-α in colitis." (PMID 25120575, 2014). "Increased expression of cytokines, such as IL-1β, IL-6, TNF-α, and interferon-γ (IFN-γ), is observed after TNBS treatment, suggesting that cytokines are involved in the pathogenesis of TNBS-induced colitis." (PMID 24995035, 2014). "The administration of polyphenols significantly suppressed the DAI score, along with reducing the histological severity of colitis and downregulating the expression of pro-inflammatory signaling factors, such as TNF-α, IL-1β and IL-6." (PMID 25409433, 2014). "We previously observed that cytokines such as IL-1β, IL-6 and MIP-2 were up-regulated in an animal model of colitis." (PMID 24520376, 2014). "Cytokines including IL-6 and TNF-α, which play a crucial role in acute DSS-induced colitis model, were analyzed." (PMID 24948848, 2014). "Here, after demonstrating the beneficial effect of central cholinergic activation by a M1mAChR agonist in DNBS-colitis, we demonstrate that this effect is accompanied by a downregulation of IFN-γ and IL-17, IL-1 β, IL-6 and TNF-α levels in colonic tissues." (PMID 25295619, 2014). "The levels of TNF-α and IFN-γ increased, but IL-6, IL-17A and IL-4 decreased in lamina propria (LP) of colon in immune milk-fed mice with DSS-induced colitis." (PMID 24686517, 2014). "In the model of colitis induced by TNBS, polysaccharides of C. montagnei showed reduced levels of IL-6 and NO, as well as others important markers, such as myeloperoxidase." (PMID 24518681, 2014).